REN (renin)
Diseases named in the same sentence as REN in open-access papers (continued):
Sharing a sentence is not in itself a finding about the gene and the disease.
Hypertension (continued). "Both the index case and her mother presented in childhood with markedly elevated aldosterone concentrations, suppressed plasma renin activity, and early-onset severe hypertension refractory to treatment, which required bilateral adrenalectomy." (PMID 33800142, 2021). "Renin-angiotensin-aldosterone system (RAAS) has been reported to play a central role in regulating hypertension and acute lung injury." (PMID 33544293, 2021). "To date, hypertension of developmental origins has been attributed to mechanisms including reduced nephron number, oxidative stress, an aberrant renin–angiotensin system (RAS), gut microbiota dysbiosis, and sex differences, among others." (PMID 34072634, 2021). "Hyperkalemia is common in patients on renin-angiotensin-aldosterone system inhibitors (RAASi) or Mineralocorticoid Receptor Antagonists (MRAs) and can affect treatment optimization for hypertension, diabetes mellitus, heart failure (HF), and CKD." (PMID 34150795, 2021). "Renin–angiotensin system inhibitors are recommended for treating hypertension with chronic kidney disease." (PMID 33323991, 2021). "These biochemical parameters are of importance in pathophysiology of hypertension and indicative of activation of renin-angiotensin system and reorganization of endothelium." (PMID 34563194, 2021). "Among cases of SARS-CoV-2 infections that result in serious conditions or death, many have pre-existing conditions such as hypertension and are on renin–angiotensin–aldosterone system (RAAS) inhibitors." (PMID 34880395, 2021). "Second, the renin-angiotensin II-aldosterone axis has been traditionally recognized as a key regulator of blood pressure in the development of hypertension, with AngII levels regulated by ACE." (PMID 33580165, 2021). "The clinical presentation was in line with a hypertension mediated by elevated renin levels, generating extremely high blood pressure, flash pulmonary edema, and signs of a hypertensive crisis with acute end organ dysfunction." (PMID 33857767, 2021). "Increased renin activity under pathological conditions has been further supported by in vivo data from different models of experimental hypertension demonstrating that PRR in the CD is required for the local formation of AngII." (PMID 34179130, 2021). "Gene polymorphisms linked to the renin–angiotensin (AGT)–aldosterone system (RAAS) were broadly inspected in patients with diabetic nephropathy (DN) and hypertension." (PMID 33668947, 2021). "The characteristic tendency to the development of hypertension is in line with the suggested interference of the coronavirus with the renin-angiotensin-aldosterone system." (PMID 33425387, 2021). "With respect to angiotensinogen, our data point towards an upregulation of the renin-angiotensin-aldosterone axis in women with MI even when controlling for the presence of hypertension and medications upon admission." (PMID 33831096, 2021). "Three hundred and sixty subjects were on pharmacological treatment for hypertension, with inhibitors of renin‐angiotensin‐aldosterone system being the most prescribed class of drugs (308 subjects)." (PMID 34129696, 2021). "RVH is hypertension resulting in alteration of the renin-angiotensin mechanism secondary to a lesion reducing blood flow to part or all of one or both kidneys." (PMID 33411105, 2021). "First, the renin-angiotensin-aldosterone system (RAAS) is over-activated, causing vasoconstriction, hypertension, elevated aldosterone levels and sympathetic tone, and eventually cardiac remodeling." (PMID 34859070, 2021). "Hypertension and respiratory inflammation are exacerbated by the Renin-Angiotensin-Aldosterone System (RAAS), which normally protects from rapidly dropping blood pressure via Angiotensin II (Ang II) produced by the enzyme Ace." (PMID 33757938, 2021). "The dysregulation of renin-angiotensin-aldosterone-system (RAAS) plays a critical role in the pathophysiology of hypertension and in the occurrence of the TOD." (PMID 34575833, 2021).
Hypertension (continued). "Rat models of CKD demonstrated decreased cholinergic responses in the presence of hypertension and elevated renin–angiotensinogen." (PMID 33234591, 2021). "Of the 42 dogs with CKD, 25 had been treated with renin‐angiotensin system inhibitors to manage proteinuria or systemic hypertension." (PMID 34418162, 2021). "Beyond mechanical stress, activation of the local renin-angiotensin system and toll-like receptor 4 pathway by systemic hypertension can induce vascular inflammation and remodeling, contributing to aneurysm rupture." (PMID 34043701, 2021). "ARBs have been reported in comprehensive studies to affect the renin–angiotensin system (RAS) by upregulating the ACE2 enzyme more than other drugs prescribed for hypertension." (PMID 33504092, 2021). "The etiology of hypertension involves a complex interplay of various elements, including genetic, neurohumoral, and environmental factors, among which the renin-angiotensin-aldosterone system (RAAS) plays a critical role in the pathogenesis of hypertension." (PMID 34393778, 2021). "Animal experiments have reported that increases in serum uric acid by inhibiting urate oxidase can increase renal renin and decrease plasma nitrate, resulting in vasoconstriction and hypertension." (PMID 33503029, 2021). "Hypertension and hypokalemia, the secondary symptoms of excessive renin secretion, are the most common presentations." (PMID 33995279, 2021). "All 14 patients had hypertension, ten had hypokalemia, and seven had elevated plasma renin activity." (PMID 33995279, 2021). "Hypertension and decreased renal blood flow are known to induce an increase in the renin–angiotensin–aldosterone (RAA) system and other specialized pathways." (PMID 34348745, 2021). "It is well known that thyroid hormones can impact the renin-angiotensin-aldosterone system, and the renin substrates are synthesized in the liver under the stimulus of T3, which results in hypertension in a hypothyroid state." (PMID 34381374, 2021). "DOCA-salt model incorporates a high-salt diet, as well as producing neurogenic and a low-renin form of hypertension, similarly to what is described in the human population." (PMID 34578849, 2021). "In total, 123 patients with PA and 40 patients with other low-renin hypertension (LRH) met all inclusion criteria." (PMID 33841329, 2021). "Hypertension-related mechanisms, like the renin-angiotensin axis, adrenergic tonus, and electrolytes imbalance are known to be up-regulated in the SHR phenotype and contribute to the low-grade systemic inflammation." (PMID 33661916, 2021). "We speculated the activation of neuro-endocrine hormone pathways, such as renin-aldosterone system and sympathetic system at periphery level in a high-risk patient of metabolic syndrome may have changed his hypertension status from masked to sustained hypertension." (PMID 33876965, 2021). "This was expected because AngII is an active hormone of the renin-angiotensin system known to play an important role in the development of hypertension." (PMID 34617056, 2021). "Renin-angiotensin activity, as an important pathogenesis of hypertension, was also reported to be increased in PAH patients, and its inhibition by losartan was beneficial in experimental PAH." (PMID 34267668, 2021). "Being young and female with a short hypertension duration, normokalemia, low creatinine level, low plasma aldosterone concentration, and low aldosterone-to-renin ratio (ARR) was significantly more common in bilateral than unilateral PA patients." (PMID 33912136, 2021). "It is difficult to restore healthy blood pressure from hypertension by the limitation of the sympathetic nervous system and renin-angiotensin-aldosterone system." (PMID 33688497, 2021). "Chronic activation of the renin-angiotensin system plays a key role in vascular remodeling and hypertension." (PMID 33054395, 2021).
Hypertension (continued). "This study suggested that exercise prevents hypertension through a mechanism that involves ncRNA-mediated regulation of the Renin-Angiotensin pathway." (PMID 34445357, 2021). "We previously showed that 2K1C hypertension increases the gastric retention of a liquid test meal in awake rats, prevented by treatment with aliskiren, captopril or losartan, blockers of renin, angiotensin-converting enzyme (ACE), and ATR1, respectively." (PMID 34777003, 2021). "In the case of a shared pathway between hypertension and COVID-19, we found that the renin-angiotensin system is the key pathway that links these two diseases." (PMID 34067609, 2021). "For this observational study, we identified randomised controlled trials (phase 2/3, 3, or 4) of renin-angiotensin-aldosterone system (RAAS) drugs for hypertension registered from 1999 onwards with ClinicalTrials.gov." (PMID 34240062, 2021). "Major alcohol-mediated mechanisms that contribute to cardiometabolic comorbidity include impaired substrate utilization and storage, endothelial dysfunction, dysregulation of the renin-angiotensin-aldosterone system, and hypertension." (PMID 35115952, 2021). "The renin–angiotensin pathway is involved in the disease pathophysiology of hypertension, diabetes, and cardiovascular disease." (PMID 34770863, 2021). "Knowledge of how matrix metalloproteinases, the immune system, the renin-angiotensin-aldosterone system and oxidative stress are involved and their role in the pathophysiology of hypertension is not yet fully understood." (PMID 34575833, 2021). "We believe that the hypertension most likely was a renin mediated equivalent to Page kidney, and that the increased levels of plasma renin were caused by DCS packing with direct compression of kidney parenchyma." (PMID 33857767, 2021). "We used the KEGG hypertension (renin-angiotensin system) pathway (hsa04614) in this analysis to identify the pathway–pathway interactions between hypertension and COVID-19." (PMID 34067609, 2021). "Arterial hypertension in these patients seems to be an effect of both hypercortisolism and increased activation of the renin–angiotensin–aldosterone system." (PMID 34659130, 2021). "The increase of renin expression was persistent until 4 months of age and was associated with elevated BP, indicating the impact of PRR on DEX-induced programmed hypertension." (PMID 33669059, 2021). "Second, several RAS-based interventions have also shown benefits in protecting against programmed hypertension, such as renin inhibitor, ACEI, ARB, and ACE2 activator." (PMID 34072634, 2021). "Hypertension is of particular interest, because components of the renin–angiotensin system (RAS), which are critically involved in the pathophysiology of hypertension, are also implicated in COVID-19." (PMID 34151246, 2021). "In the case of hypertension secondary to kidney injury, termed Page kidney injury, renin hypersecretion occurs in response to the renal hematoma." (PMID 33496864, 2021). "The involvement of vitamin D deficiency in cardiovascular disease is supported by experimental studies showing myocardial hypertrophy, arterial hypertension and increased activity of the renin-angiotensin system in vitamin D receptor knockout mice." (PMID 34690803, 2021). "The DOCA-salt model can be thought to mimic, at least to some extent, the low-renin hypertension in humans." (PMID 33651165, 2021). "This review gives an overview of the pathophysiological effects of the Coronavirus Disease 2019 (COVID‐19) in relation to hypertension, with a focus on the Renin–Angiotensin–Aldosterone–System and the MAS receptor." (PMID 34121359, 2021). "The inhibition of renin and ACE in the RAS pathway is considered an important therapeutic strategy in treating hypertension which is a controllable risk factor for cardiovascular diseases." (PMID 34681387, 2021). "Renin is another target to control hypertension because this enzyme generates angiotensin I from angiotensinogen." (PMID 34828976, 2021).
Hypertension (continued). "Transforming growth factor-β (TGF-β) is a key driver of renal fibrosis, especially when activating renin-Ang system (RAS), which is the main cause of hypertension." (PMID 34084130, 2021). "Abnormal RAS system was related to hypertension; here, we showed increased renin and AT1 expression in miR‐TKO mice compared with WT mice." (PMID 34197043, 2021). "It was recently also demonstrated that the elevated serum concentration of bradykinin, des-Arg can lead to the decreased activity of renin-angiotensin, which was related to hypertension and other metabolic diseases." (PMID 34721534, 2021). "The objective of this review is to give an overview of the pathophysiological effects of the Coronavirus Disease 2019 (COVID‐19) in relation to hypertension (HT), with a focus on the Renin–Angiotensin–Aldosterone System (RAAS) and the MAS receptor." (PMID 34121359, 2021). "Two well-described physiological systems that are over activated in hypertension are the sympathetic nervous system and the renin-angiotensin-aldosterone system." (PMID 33394136, 2021). "Although there were several patients with hypertension, median values of blood pressure percentiles and plasma renin activity were in normal ranges." (PMID 33155789, 2021). "There are also reports of renin-angiotensin inhibitors improving outcomes in COVID-19 patients with hypertension." (PMID 34414048, 2021). "Transforming growth factor-β (TGF-β) is a key driver of renal fibrosis, especially when activating the renin–Ang system (RAS), which is the main cause of hypertension." (PMID 34084130, 2021). "Excessive licorice consumption can lead to hyper mineralocorticoidism, a condition marked by salt retention, hypokalemia, hypertension, metabolic alkalosis, hypoaldosteronism, and low renin activity." (PMID 34961221, 2021). "We encourage considering this unusual but important mechanism when packing the abdomen, and strongly recommend ruling out renin-mediated hypertension in cases who start showing hypertension episodes after surgery." (PMID 33857767, 2021). "Increased activation of the renin–angiotensin–aldosterone system (RAS) is an important factor in hypertension pathogenesis." (PMID 34456867, 2021). "Most patients with hypertension have dysfunction of the renin–angiotensin–aldosterone system, water and sodium retention are increased with more interstitial fluid and decreased plasma content in blood vessels, resulting in increased blood viscosity." (PMID 33771148, 2021). "In SHR, hypertension is generally attributed to the increased activity of the sympathetic nervous system, hyperactivation of the renin-angiotensin-aldosterone system, and endothelial dysfunction mainly due to the reduced bioavailability of NO." (PMID 34819984, 2021). "17β-Estradiol has been reported to protect rats from aldosterone-induced hypertension, and sex differences in the renin-angiotensin-aldosterone system have been reported." (PMID 34363052, 2021). "As an exemplar, here we focus on drugs to treat hypertension acting on the renin-angiotensin-aldosterone system (RAAS)." (PMID 34240062, 2021). "LXRs are thought to regulate hypertension by inhibiting the renin-angiotensin-aldosterone system (RAAS) and by increasing the expression of cardiac natriuretic peptides." (PMID 34360540, 2021). "Angiotensin-converting enzyme 2 (ACE2) protects against organ damage in hypertension and cardiovascular diseases by counter regulating the renin-angiotensin system (RAS)." (PMID 33750913, 2021). "Angiotensin II (Ang II) regulates hypertension by the renin-angiotensin system and the stimulation of NOX in vascular walls." (PMID 34439468, 2021). "We examined the effect of total and afferent renal denervation (RDN) on hypertension and the renin-angiotensin system (RAS) in a rodent model of juvenile-onset polycystic kidney disease (PKD)." (PMID 34253766, 2021).
Hypertension (continued). "Abnormalities in the renin-angiotensin system (RAS) have been implicated in a number of forms of clinically significant elevated blood pressure, including essential hypertension." (PMID 34674633, 2021). "Heart failure and high blood pressure are usually associated with SAN dysfunction, which is characterized by excessive activation of renin-Ang II signaling and elevated ROS levels." (PMID 33936239, 2021). "The role of high blood pressure and the renin–angiotensin–aldosterone system is well recognized, but the pathogenesis of the renal injury of malignant hypertension (MH) remains incompletely understood." (PMID 34528115, 2021). "The RAS (renin-angiotensin system) is the part of the endocrine system that plays a prime role in the control of essential hypertension." (PMID 34925551, 2021). "These comprised phenotypes potentially related to COVID-19 pathophysiology, such as high blood pressure, agents acting on the renin-angiotensin system, and mean corpuscular hemoglobin." (PMID 34834519, 2021). "Previous studies have explored potential mechanisms linking adiposity and high blood pressure, including sympathetic nervous system activation, activation of the renin–angiotensin system, inflammatory responses, and insulin resistance." (PMID 34176482, 2021). "Angiotensin-converting enzyme inhibitor (ACEi) and angiotensin receptor blockers (ARBs) are primary line of medications for management of high blood pressure through inhibitory effect towards renin-angiotensin-aldosterone system (RAAS)." (PMID 33544293, 2021). "Among the well-known pathophysiological elements leading to essential hypertension, the renin–angiotensin–aldosterone system (RAAS) has a vital role." (PMID 34759820, 2021). "Patients with essential hypertension also have a blunted suppression of renin in response to saline loading." (PMID 34285286, 2021). "The increased incidence of essential hypertension and DM and enhanced plasma renin activity in patients with psoriasis is of special interest." (PMID 34071993, 2021). "The pathophysiology of hypertension is multifactorial and related to activation of the sympathetic nervous system, renin-angiotensin-aldosterone system, pro-inflammatory mediators, endothelial dysfunction, and increased oxidative stress." (PMID 32194403, 2020). "Both peripheral and brain renin-angiotensin systems play a fundamental role in hypertension, hence ACE inhibitors are currently used to treat it." (PMID 32470081, 2020). "The inhibition of ACE function is also one of the widely used therapeutic options in the hypertension disease as this enzyme is involved in the renin-angiotensin axis of blood pressure regulation which is largely involved in the pathogenesis of hypertension." (PMID 33082415, 2020). "Aliskiren, the first effective direct oral renin inhibitor approved for the treatment of hypertension, acts by suppressing the first and rate-limiting step of the RAAS leading to more complete blockade of this system." (PMID 33145109, 2020). "All cases had symptoms of hypertension, hyperaldosteronism, high plasma renin, high plasma angiotensin II." (PMID 32441904, 2020). "Currently, the role of (pro)renin on the stimulation of distal Na+ reabsorption in hypertension is being actively investigated, particularly due to the presence of the (pro)renin receptor (PRR) in the CD." (PMID 33281610, 2020). "One preliminary clinical study reported that treatment with renin inhibitor aliskiren, as an antihypertensive agent, is effective and safe for severe COVID-19 patients complicated with hypertension." (PMID 33244381, 2020). "Endocrinopathy such as IR and high renin-angiotensin activity was documented in several previous reports that investigated pathogenesis of hypertension and BA." (PMID 33330745, 2020). "Models of pregnancy-induced hypertension such as the reduced utero-placental pressure and renin-angiotensin system in rats, demonstrate imbalance in vascular tone." (PMID 33244052, 2020).